RNU6-12P (RNA, U6 small nuclear 12, pseudogene)
Synonyms: RNU6-12
Gene: Small nuclear RNA gene on chromosome 8 (118,976,513 to 118,976,619, forward strand). Ensembl gene ENSG00000207334.
Homologues: Orthologues: mouse Gm22821 (100% identical), pig U6 (89% identical). Paralogues in human: RNU6-13P (100% identical), RNU6-32P (100% identical), RNU6-1 (99% identical), RNU6-17P (99% identical), RNU6-18P (99% identical), RNU6-2 (99% identical), RNU6-3P (99% identical), RNU6-4P (99% identical), RNU6-5P (99% identical), RNU6-6P (99% identical), RNU6-9 (99% identical), RNU6-25P (98% identical), and 1290 more.